HLA-DQB1 (major histocompatibility complex, class II, DQ beta 1)
Diseases named in the same sentence as HLA-DQB1 in open-access papers (continued):
Sharing a sentence is not in itself a finding about the gene and the disease.
COVID-19 (9 papers, 2021 to 2024). A disease caused by infection with severe acute respiratory syndrome coronavirus 2. "In the case of SARS-CoV-2 infection, HLA-A*11, HLA-C*01, and HLA-DQB1*04 are associated with mortality by COVID-19, whereas another HLA, such as HLA-A:02:01, is implicated in the activation of T cells." (PMID 35062298, 2022). "It has been previously reported that ∼25% of the Thai population carried HLA-DQA1/HLA-DQB1 genetic polymorphisms, which might render COVID-19 severity." (PMID 35250581, 2022). "Determination of HLA genetic polymorphisms showed that the alleles HLA-A*11, HLA-C*01, and HLA-DQB1*04 could be associated with mortality at 30 days for patients with COVID-19." (PMID 35062298, 2022). "We identified SNPs in Class II HLA genes, HLA-DRB1, and HLA-DQB1 previously noted to be strongly repressed in a dominant population of dendritic cells, in acute cases of COVID-19, in cohort 1 and 2, respectively." (PMID 36143338, 2022). "A recent study from Italy showed an increase in the frequency of HLA-B*27:07, HLA-DRB1*15:01, and HLA-DQB1*06:02 among severe COVID-19 patients in a cohort of 99 Italians." (PMID 35250581, 2022). "Consistently, DCs from COVID-19 patients also displayed lower antigen presentation capacity than healthy donors, with genes associated with antigen presentation (e.g., HLA-DQB1, HLA-DEB5 and HLA-DQA1, etc.)downregulated in DCs from the COVID-19 groups including those with encephalopathy." (PMID 37848421, 2023). "We observed that certain genes in the severe COVID-19 gene set, such as IFI27, HLA-DQB1, and CLU, also hold significance in the context of influenza patient classification." (PMID 39350339, 2024). "Expression levels of major histocompatibility complex class II molecules, including HLA-DRA, HLA-DRB5, HLA-DPA1, and HLA-DQB1, which are expected to be increased following MAC activation in the COVID-19 group, were found to decrease." (PMID 38441496, 2024). "In contrast, expression of MHC-II genes (HLA-DQB1, HLA-DPB1 and HLA-DQA1, etc.)were decreased in COVID-19 acute necrotizing encephalopathy patients, indicating an immune paralysis of T cells." (PMID 37848421, 2023). "Further, we investigated the expression of MHC class II molecules (MHCII) and Fc receptors (FcRs) and found that they were broadly upregulated in APCs in lungs of mild COVID-19 patients, with a MHCII subset (HLA-DRA, HLA-DMB, HLA-DRB1, HLA-DPB1, HLA-DQB1, HLA-DMA) were downregulated." (PMID 34502134, 2021). "Furthermore, we found significant downregulation of most of HLA class II genes (HLA-DRB5, HLA-DQB1 and HLA-DQA2, etc.)in B cells from COVID-19 patients, especially in the severe and acute necrotizing encephalopathy groups, indicating dysregulated crosstalk between adaptive immune cells." (PMID 37848421, 2023).
Autoimmunity (8 papers, 2012 to 2025). The occurrence of an immune reaction against the organism's own cells or tissues. "BP represents a complementary autoimmune model, where shared neuronal and epidermal expression of BP180 (collagen XVII) and BP230, together with the HLA-DQB1*03:01 allele, support a neurocutaneous autoimmunity hypothesis." (PMID 41465136, 2025). "In our studies, using the Caucasian MS-associated allelic genes (of the HLA-DR15 haplotype) we show the opposite scenario for the role of the HLA-DQ6 in anti-myelin autoimmunity in HLA-Tg mice, as the HLA-DQB1*0602 gene product determined susceptibility to PLP- as well as to MOBP-induced EAE." (PMID 22316121, 2012). "A blood brain barrier phenotype is present as well as autoimmunity and autophagy with ANO2, HLA-DQB1, MTMR3, and SEC16A." (PMID 31026304, 2019). "Our results show that, unlike the previously reported HLA-DR-dependent susceptibility to MBP-, PLP-, or MOG-induced EAE, the pathogenic autoimmunity against PLP, as well as against MOBP, was dependent on HLA-DQB1*0602 rather than HLA-DRB1*1501." (PMID 22316121, 2012).
agranulocytosis (7 papers, 2015 to 2024). "Certain HLA alleles, such as HLA-DRB1*04:02, HLA-DPB1*05:02, HLA-DQB1 (126Q), HLA-B (158T), and HLA-B*59:01, have been reported to be associated with clozapine-induced agranulocytosis." (PMID 38516266, 2024). "Another study showed that the HLA-DQB1 6672G>C (rs113332494) variant significantly increased the risk of developing neutropenia and agranulocytosis in individuals of European ancestry, with a notably higher odds ratio for agranulocytosis than for neutropenia." (PMID 38921968, 2024). "HLA-DQB1 (6672G>C, rs113332494) was associated with neutropenia (OR = 6.20, P = 2.20E−06) and agranulocytosis (OR = 10.49, P = 1.83E−06) in individuals of European ancestry." (PMID 33846298, 2021). "Our study shows an association between rs113332494 (HLA-DQB1 6672G>C) and clozapine-induced neutropenia and agranulocytosis, further adding to the evidence of the importance of this genetic variant." (PMID 33846298, 2021). "The HLA-DQB1 variant had high specificity, but low sensitivity in predicting risk for agranulocytosis and neutropenia." (PMID 33846298, 2021). "Several studies identified HLA-DQB1 variants and especially a polymorphism located in HLA-DQB1 (6672G>C, rs113332494) as associated with clozapine-induced agranulocytosis and neutropenia." (PMID 33846298, 2021). "We performed an association analysis of the marker HLA-DQB1 6672G>C (rs113332494) in a European sample comprised of 871 controls, 133 neutropenia and 54 agranulocytosis cases." (PMID 33846298, 2021). "In summary, we were able to replicate previous findings for an association of rs113332494 (HLA-DQB1 6672G>C) with clozapine-induced neutropenia and agranulocytosis in individuals of European ancestry." (PMID 33846298, 2021). "The human leukocyte antigen (HLA) region has been associated with genetic susceptibility to clozapine-induced agranulocytosis (single amino acid changes in HLA-DQB1 (126Q) and HLA-B (158T))." (PMID 29298994, 2019). "Finally, an HLA-DQB1 variant (6672G/C, rs113332494) was robustly associated with clozapine-induced agranulocytosis." (PMID 38399298, 2024). "Only variants in HLA-DQB1 were significantly associated with agranulocytosis in both cohorts." (PMID 33846298, 2021). "Our study further strengthens the evidence implicating HLA-DQB1 in agranulocytosis and neutropenia, suggesting components of the immune system as contributing to this serious adverse drug reaction." (PMID 33846298, 2021). "This estimate approximates a previous estimation with higher agranulocytosis prevalence but with a lower, single HLA-DQB1 genotyping sensitivity." (PMID 29298994, 2019). "Combining HLA-DQB1 with HLA-B epitope testing increased the sensitivity for CIA prediction to 41% (CI 95%: 31–51%) and showed a 30% reduction in the lower risk group (a reduction in CIA incidence from 0.7% to <0.5%), which approximates the agranulocytosis risk of other antipsychotics." (PMID 29298994, 2019). "The proposed test of HLA-DQB1 6672G>C has high specificity, but low sensitivity fails to reduce the agranulocytosis risk in the LR group sufficiently that monitoring could be reduced or ceased." (PMID 25732907, 2015).
leprosy (7 papers, 2015 to 2022). Leprosy is a chronic infectious disease affecting primarily the skin and peripheral nervous system. "For HLA class II (HLA-DR and DQ), the most consistent findings are that HLA-DR2 (subtypes HLA-DRB1*15 and HLA-DRB1*16) and HLA-DQ1 (subtypes HLA-DQB1*05 and HLA-DQB1*06) are associated with the TT and LL clinical forms, respectively, and are also associated with leprosy per se." (PMID 25605482, 2015). "Similarly, 7 of the 9 SNPs significantly heterogeneous between T1R and leprosy were eQTLs in either whole blood, rs3774937 (NFKB1), rs10065637 (ANKRD55), rs11150589 (ITGAL) and rs2836878 (lncRNA ENSG00000235888) or multiple tissues, rs4664304 (LY75), rs113653754 (HLA-DQB1) and rs4768236 (LRRK2)." (PMID 28222097, 2017).
type 2 diabetes (7 papers, 2013 to 2025). "Similarly, specific HLA-DQA1 and HLA-DQB1 genes have been associated with susceptibility to type 2 diabetes mellitus (T2DM)." (PMID 40771282, 2025). "Second, the distinct lipid pattern observed by HLA-DQB1*0302 genotype may reflect etiologically distinct subgroups of adult-onset diabetes." (PMID 36269708, 2022).
Allergy (6 papers, 2011 to 2024). An allergy is an immune response or reaction to substances that are usually not harmful. "HLA-DQB1 is the major histocompatibility complex (class II) antigens that have been identified as useful biomarkers of candidacy for effective allergy immunotherapy in patients with AR." (PMID 33644074, 2021).
breast carcinoma (6 papers, 2009 to 2021). "For individual cancer sites, we only observed nominally significant associations with breast cancer for homozygosity at HLA-C locus (adjusted OR = 1.38, 95% CI = 1.02–1.87, P = 0.036) and lung cancer for homozygosity at HLA-DQB1 locus (adjusted OR = 1.15, 95% CI = 1.02–1.29, P = 0.022)." (PMID 34421988, 2021). "However, HLA-DQB1 and HLA-G +3142C>G (rs1063320) polymorphisms were related to increased breast cancer susceptibility." (PMID 33659210, 2020).
sarcoidosis (6 papers, 2019 to 2025). Sarcoidosis is a multisystemic disorder of unknown cause characterized by the formation of immune granulomas in involved organs. "HLA-DQB1 was another HLA class II locus containing sarcoidosis-associated variant in Koreans, specifically HLA-DQB1*03:02 as a protective factor." (PMID 35661780, 2022). "Two variants upstream from an intronic/exonic border region of HLA-DQB1 were also significantly associated with sarcoidosis, rs4516985 and rs9274614 (ORs = 1.74 and 2.49, respectively)." (PMID 31126090, 2019). "There was a strong association with sarcoidosis within exonic regions of the HLA-DQB1 gene, represented by rs1049133 and rs1049130, two SNPs 12bp apart (ORs = 2.56 and 1.90, respectively)." (PMID 31126090, 2019). "HLA-DQB1*06:02 and HLA-DQB1*06:04 can be considered as susceptibility (risk) factors for sarcoidosis; the frequency of the HLA-DQB1*06:02 in the patients was increased 1.75 times compared with the control subjects, and the HLA-DQB1*06:04 frequency increased four times in the patients." (PMID 37153085, 2023). "Regarding clinical phenotypes of sarcoidosis, HLA-A*01:01, HLA-B*08:01, HLA-C*07:01, HLA-DRB1*03:01, HLA-DQA1*05:01, and HLA-DQB1*02:01 associated with Löfgren’s syndrome." (PMID 37153085, 2023). "Further, we suggest new HLA variants associated with sarcoidosis risk (e.g., HLA-DQA1*05:08) and novel protective variants HLA-DQB1*03:02 and HLA-DQA1*01:02 in Koreans." (PMID 35661780, 2022).
schizophrenia (6 papers, 2020 to 2025). A major psychotic disorder characterized by abnormalities in the perception or expression of reality. "Numerous studies have demonstrated association between HLA alleles (HLA-A9, HLA-A10, HLA-DRB1, HLA-DQB1) and schizophrenia susceptibility." (PMID 31642026, 2020). "Currently, there are convincing evidence that allelic variants of HLA genes, including HLA-DQB1*0602 and HLA-DRB1*04, can affect the risk of schizophrenia." (PMID 40416497, 2025). "No studies have been conducted on specific mechanisms of HLA-C, HLA-DRB1, and HLA-DQB1’s interventions in schizophrenia pathogenesis, but their interaction is much likely to contribute to the disease." (PMID 34805976, 2021). "The interaction among HLA-C, HLA-DRB1, and HLA-DQB1 is likely to take part in schizophrenia’s pathogenesis as well." (PMID 34805976, 2021). "The strongest secondary signal was observed for rs9273325 (HLA-DQB1), which was negatively associated with VZV antibody response and positively associated with schizophrenia susceptibility (OR = 1.13, P = 4.3 × 10−15)." (PMID 33109261, 2020).
hypothyroidism (5 papers, 2016 to 2024). Abnormally low levels of thyroid hormone. "We also report novel SNP associations for hypothyroidism near HLA-DQA1/HLA-DQB1 at rs6906021 (combined odds ratio (OR)=1.2 (95% confidence interval (CI): 1.1–1.2), P=9.8 × 10−11) and for polymyalgia rheumatica near C6orf10 at rs6910071 (OR=1.5 (95% CI: 1.3–1.6), P=1.3 × 10−10)." (PMID 27109359, 2016). "For hypothyroidism, the strongest 4-digit allelic associations were seen at the HLA-DQA1*0501, HLA-DQB1*0201, HLA-DRB1*0301 alleles (P<10−6 for each allele), which collectively comprise the HLA-DR3-DQ2 haplotype." (PMID 27109359, 2016). "Some data showed that HLA-DQB1*03 is connected to both AA and antibodies-induced hypothyroidism." (PMID 39205687, 2024). "Hypothyroidism has 4 genes (HLA-DPA1, HLA-DQB1, HLA-DQA1, and HLA-DPB1, where two have 5% of predictor variance each and two have 1% each) out of its top 17 genes included among the 641 potentially problematic genes, while 8% is the highest value of predictor variance accounted for by a single gene." (PMID 32694572, 2020).
vitiligo (5 papers, 2019 to 2025). Generalized well circumscribed patches of leukoderma that are generally distributed over symmetric body locations and is due to autoimmune destruction of melanocytes. "Additionally, in Brazil, HLA-DQB1*06 has been correlated with susceptibility to vitiligo (common, acrofacial and mixed), while HLA-A*32 has been correlated with the localized form (focal and segmental)." (PMID 35643735, 2022). "Variants in HLA genes, particularly HLA-DQB1 and HLA-DRB1, are strongly linked to increased susceptibility to vitiligo." (PMID 39860439, 2025). "HLA alleles implicated in vitiligo and found so far are HLA-DRB4*0101, HLA-DQB1*0303, HLA-DRB1*03, HLA-DRB1*04, HLA-DRB1*07, and HLA DRB1A*04-(DQA1*0302)-DQB1*0301." (PMID 36902341, 2023). "In this study, we identified new susceptibility signals associated with risks of vitiligo (rs113465897, rs3130969, HLA-DPB1*0301) and SLE (rs3129898) and confirmed a reported allele, HLA-DQB1*0301, to be associated with SLE." (PMID 35082778, 2021). "Using Beagle 4.1, we successfully imputed the SNV, CNV, two–digit and four–digit alleles of HLA genes (HLA-A, HLA-B, HLA-C, HLA-DQA1, HLA-DQB1, HLA-DPA1, HLA-DPB1, HLA-DRB1) and amino acids of 2810 vitiligo subjects (1117 cases, 1693 controls) and 2739 SLE subjects (1,693 controls and 1,046 cases)." (PMID 35082778, 2021). "To dissect the relative contributions of rs149554018, rs9271597, and the classical HLA alleles to vitiligo risk, we compared logistic regression models with haplotypes defined by different combinations of rs145954018, HLA-DRB1*13:01, rs9271597, HLA-DQA1*01:03, and HLA-DQB1*06:03." (PMID 30674883, 2019).
acute lymphoblastic leukemia (4 papers, 2016 to 2025). Leukemia with an acute onset, characterized by the presence of lymphoblasts in the bone marrow and the peripheral blood. "In our investigation, the HLA-DQB1*05 gene was identified as a genetic risk factor specifically for juvenile acute lymphoblastic leukemia (ALL)." (PMID 40508101, 2025). "For fludarabine, SMC4 associated with the outcome of pediatric acute lymphoblastic leukemia, and TNFRSF13C and HLA-DQB1 for which specific gene variants had been associated with different types of leukemia were included." (PMID 41146244, 2025). "The HLA-DQB1*05 gene showed significantly elevated expression in children with acute lymphoblastic leukemia (ALL) compared to healthy controls in Iranian research." (PMID 40508101, 2025). "However, most patients evaluated by Schaap and coworkers were diagnosed with acute lymphoblastic leukemia (ALL), donors were HLA-A, HLA-B, HLA-DRB1, and HLA-DQB1-identical siblings, and all patients who were evaluated received TCD grafts." (PMID 34950586, 2021).
depression (4 papers, 2020 to 2025). "The allele with strongest evidence for association with depression was HLA-B*08:01, followed by HLA-DQB1*02:01 and HLA-DRB1*03:01." (PMID 31570195, 2020). "In fact, many of the depression-associated genes that underwent positive selection in both African and South Asian populations are immune-related, such as HLA-DQA1, HLA-DQB1, and MGAT4C." (PMID 40075226, 2025).
hepatocellular carcinoma (4 papers, 2013 to 2025). A malignant tumor that arises from hepatocytes. "Infection with the hepatitis B virus (HBV) is an independent risk factor for liver cirrhosis and hepatocellular carcinoma, polymorphisms in HLA-DQB1 play an important role in HBV infections." (PMID 30563535, 2018).
lung adenocarcinoma (4 papers, 2021 to 2025). A carcinoma that arises from the lung and is characterized by the presence of malignant glandular epithelial cells. "For example, some studies have shown that tumor HLA-DQB1 level is associated with the recurrence free survival (RFS) of early Lung Adenocarcinoma, and the mechanism may be related to anti-tumor immunity." (PMID 34938740, 2021). "Studies have shown that lower expression levels of HLA-DQB1 in lung adenocarcinoma tissue correlate with a reduced recurrence rate in patients, indicating its significant role in the immune response and prognosis of lung adenocarcinoma." (PMID 38942606, 2024). "In lung adenocarcinoma, high expression of CCL20, IL23A, MMP1 and MMP3 was significantly associated with poor patient prognosis, whereas high expression of FOS, HLA-DPA1, HLA-DPB1, HLA-DQA1, HLA-DQB1 and HLA-DRA was significantly associated with improved patient prognosis." (PMID 40016789, 2025).
lymphoma (4 papers, 2015 to 2024). A malignant (clonal) proliferation of B- lymphocytes or T- lymphocytes which involves the lymph nodes, bone marrow and/or extranodal sites. "Significantly increased allele frequencies of HLA-DQA1*01:03 and HLA-DQB1*06:01 have also been reported in lymphoma." (PMID 38593173, 2024).
neutropenia (4 papers, 2017 to 2024). A decrease in the number of neutrophils found in the blood. "We now know that the genetic etiology of clozapine-associated neutropenia is complex and is likely to involve variants from several genes including HLA-DQB1, HLA-B and SLCO1B3/SLCO1B7." (PMID 30767710, 2019).
Achalasia (3 papers, 2018 to 2023). A disorder of esophageal motility characterized by the inability of the lower esophageal sphincter to relax during swallowing and by inadequate or lacking peristalsis in the lower half of the body of the esophagus. "HLA-DQB1 has been reported to be associated with idiopathic achalasia." (PMID 35509690, 2022). "Thirteen genes associated with risk alleles of achalasia exhibited differential expression in C1QC+ macrophages, including CUTA and HLA-DQB1, compared with 18 risk genes that overlapped with DEGs in TRM, including HLA-DRB1 and HLA-DPB1." (PMID 37542039, 2023). "Maximum likelihood analysis revealed that the HLA-DQB1 locus in patients with achalasia and the HLA-DRB1 locus in controls had marginal significant deviations from Hardy-Weinberg equilibrium (HWE) after Bonferroni correction (p <0.05)." (PMID 30092016, 2018). "Gene frequencies of HLA-DQB1 in achalasia patients and healthy controls." (PMID 30092016, 2018).
Cataplexy (3 papers, 2013 to 2024). A sudden and transient episode of bilateral loss of muscle tone, often triggered by emotions. "The presence of the HLA-DQB1*0602 allele, a variant of the HLA-DQB1 gene, in the North American Caucasian population with narcolepsy and cataplexy is as high as 95%." (PMID 38565187, 2024). "Some exhibit the HLA-DQB1*0602 allele, along with cataplexy, sleep hallucinations, and sleep paralysis." (PMID 38565187, 2024).
dyslipidemia (3 papers, 2016 to 2022). "Among the patients with NT2, our results indicated that patients who were HLA-DQB1*06:02 positive had a significantly higher incidence of hypertension and dyslipidemia than that had by those who were HLA-DQB1*06:02 negative." (PMID 35627822, 2022).